RHPN1 (rhophilin Rho GTPase binding protein 1)
Description:
Has no enzymatic activity. May serve as a target for Rho, and interact with some cytoskeletal component upon Rho binding or relay a Rho signal to other molecules.
Synonyms: KIAA1929; RHPN; ODF5; RHOPHILIN
Tractability: PROTAC: ubiquitination databases record sites on it.
Gene: Protein-coding gene on chromosome 8 (143,368,810 to 143,384,221, forward strand). Ensembl gene ENSG00000158106.
Subcellular location (Human Protein Atlas): Nucleoplasm
Pathways (Reactome):
Signal Transduction: RHO GTPases Activate Rhotekin and Rhophilins; RHOA GTPase cycle
Gene Ontology:
Molecular function: protein binding
Biological process: negative regulation of stress fiber assembly; signal transduction
Cellular component: cytosol
Genetic constraint (gnomAD): Loss-of-function variants: 77 observed, 58 expected, observed/expected ratio (o/e) 1.33, 90% interval 1.1 to 1.61. The synonymous counts are far from expectation, so gnomAD's model fits this gene poorly and the ratio says little. Missense variants: 983 observed, 825 expected, observed/expected ratio (o/e) 1.19, 90% interval 1.13 to 1.26. Synonymous variants: 439 observed, 362.6 expected, observed/expected ratio (o/e) 1.21, 90% interval 1.12 to 1.31.
Homologues: Orthologues: chimpanzee RHPN1 (99% identical), macaque RHPN1 (94% identical), guinea pig RHPN1 (73% identical), pig RHPN1 (73% identical), dog RHPN1 (73% identical), mouse Rhpn1 (72% identical), rat Rhpn1 (71% identical), tropical clawed frog rhpn1 (53% identical), zebrafish rhpn1 (50% identical), Drosophila melanogaster Rhp (36% identical), Caenorhabditis elegans ego-2 (23% identical). Paralogues in human: RHPN2 (42% identical).
Diseases named in the same sentence as RHPN1 in open-access papers:
RHPN1 is named in the same sentence as 8 diseases in open-access papers, as found by Europe PMC text mining. Sharing a sentence is not in itself a finding about the gene and the disease. The quoted sentences say what the papers report.
breast carcinoma (2 papers, 2021 to 2022). "Additionally, c-Myc targets the antisense RNA 1 of the lncRNA RHPN1, which promotes breast cancer cell proliferation." (PMID 34490239, 2021).
triple-negative breast carcinoma (2 papers, 2020 to 2021). An invasive breast carcinoma which is negative for expression of estrogen receptor (ER), progesterone receptor (PR), and human epidermal growth factor receptor 2 (HER2). "A recent study using triple negative breast cancer cells suggests that ROPN1 activates RhoA signalling via rhophilin-1 (RHPN1), promoting cell migration, invasion and metastatic potential." (PMID 33918976, 2021).
Impaired glucose tolerance (1 paper, 2020). An abnormal resistance to glucose, i.e., a reduction in the ability to maintain glucose levels in the blood stream within normal limits following oral or intravenous administration of glucose. "Expression of Sorl1 and Rhpn1 is affected via a loss of miR-193b binding, which can be associated to increased fat mass and impaired glucose tolerance of NZO mice." (PMID 32350386, 2020).
cancer (4 papers, 2019 to 2025). A tumor composed of atypical neoplastic, often pleomorphic cells that invade other tissues. "The CCLE database analysis demonstrated that the two hub gene expression level of CBR3 and RHPN1 ranked higher in a variety of cancer cell line." (PMID 31285391, 2019). "The three central genes, CBR3, SF3B6, and RHPN1, might play important roles in malignancy cancer transformation." (PMID 34876005, 2021).
RHPN1 also shares sentences with these, for which no sentence is quoted: cervical cancer (1 paper); epithelial ovarian cancer (1); melanoma (1); tumor (1).